DUXA (double homeobox A)
Description:
Transcription factor that acts as a repressor.
Tractability: PROTAC: ubiquitination databases record sites on it.
Gene: Protein-coding gene on chromosome 19 (57,154,021 to 57,167,485, reverse strand). Ensembl gene ENSG00000258873.
Subcellular location: Nucleus
Pathways (Reactome):
Developmental Biology: Zygotic genome activation (ZGA)
Gene Ontology:
Molecular function: sequence-specific double-stranded DNA binding; DNA-binding transcription factor activity, RNA polymerase II-specific; RNA polymerase II transcription regulatory region sequence-specific DNA binding; DNA binding
Biological process: regulation of transcription by RNA polymerase II
Cellular component: chromatin; nucleoplasm; nucleus
Genetic constraint (gnomAD): Loss-of-function variants: 24 observed, 28.61 expected, observed/expected ratio (o/e) 0.84, 90% interval 0.61 to 1.18. The upper end of that interval is the gene's LOEUF score, 1.18, which puts it in group 5 of 6, group 1 being the genes least tolerant of losing a copy. Missense variants: 246 observed, 252.57 expected, observed/expected ratio (o/e) 0.97, 90% interval 0.88 to 1.08. Synonymous variants: 90 observed, 84.16 expected, observed/expected ratio (o/e) 1.07, 90% interval 0.9 to 1.27.
Homologues: Orthologues: chimpanzee DUXA (99% identical). Paralogues in human: CRX (22% identical), OTX2 (21% identical), PAX3 (21% identical), PAX7 (21% identical), PITX2 (21% identical), PITX3 (21% identical), ALX3 (21% identical), DPRX (21% identical), OTX1 (21% identical), PITX1 (21% identical), RAX2 (20% identical), ALX1 (20% identical), and 38 more.
Diseases named in the same sentence as DUXA in open-access papers:
DUXA is named in the same sentence as 4 diseases in open-access papers, as found by Europe PMC text mining. Sharing a sentence is not in itself a finding about the gene and the disease. The quoted sentences say what the papers report.
corneal dystrophies (1 paper, 2023). "Finally, the presence of a missense variant in heterozygosis in the DUXA gene associated with corneal dystrophies such as PPCD p.(Pro40Ser) stands out for its role in development." (PMID 37895187, 2023).
facioscapulohumeral muscular dystrophy (1 paper, 2025). An autosomal dominant disorder affecting the skeletal muscles of the face, scapula, and upper arm. "In humans, these consist of the three paralogues DUXA, DUXB and DUX4, of which only DUX4 has been extensively characterised due to its roles in facioscapulohumeral muscular dystrophy (FSHD) and multiple cancers." (PMID 40940582, 2025).
Obesity (1 paper, 2022). Accumulation of substantial excess body fat. "As a result, we found GWAS signals relevant to obesity around rs2870099 as follows: rs34863160 (ZNF470), rs11670527 (DUXA, ZNF264), and rs16987303 (ZNF471) were associated with birth weight, BMI, and height, respectively." (PMID 36276968, 2022).
DUXA also shares sentences with these, for which no sentence is quoted: keratoconus (1 paper).